GKN2 (gastrokine 2)
Diseases named in the same sentence as GKN2 in open-access papers:
GKN2 is named in the same sentence as 17 diseases in open-access papers, as found by Europe PMC text mining. Sharing a sentence is not in itself a finding about the gene and the disease. The quoted sentences say what the papers report.
gastric cancer (21 papers, 2009 to 2024). A primary or metastatic malignant neoplasm involving the stomach. "In particular, GKN2, an abomasum-specific gene that is associated with oxidative stress-induced gastric cancer cell apoptosis, showed increased expression with time." (PMID 38730227, 2024). "Molecular biology assays were performed to elucidate the function and underlying mechanisms of GKN2 in gastric cancer under stress-induced condition in vivo and in vitro." (PMID 31382983, 2019). "The effects of gastrokine-2 protein on the regulation of gastric cancer cell viability and the underlying mechanism were investigated." (PMID 25270871, 2014). "GKN1 and GKN2 have been identified based on their frequent loss of expression in neoplastic gastric carcinoma epithelial cells, compared to normal gastric tissue." (PMID 24460791, 2014). "Overexpression of Gkn2 could be associated with the prognosis of gastric cancer patients, as shown to inhibit gastric cancer cell proliferation, migration, and invasion." (PMID 32231118, 2020). "Gastrokine-2 is a putative gastric cancer-specific tumor suppressor gene, the loss of which is known to be involved in the development and progression of gastric cancer, and restoration of gastrokine-2 expression inhibits growth of gastric cancer cells in vitro." (PMID 25270871, 2014). "Gastrokine 2 stimulates apoptosis of gastric cancer cells by inhibiting NF-κB signaling and by activating JNK signaling pathway, while granzymes are expressed on cytotoxic T lymphocytes and NK cells to induce cell death." (PMID 38245882, 2024). "GKN1 and GKN2 are mainly expressed in the stomach, and decreased GKN1 expression has been linked to gastric cancer." (PMID 39300663, 2024). "The overexpression of GKN2 inhibits the proliferation, migration, and invasion of gastric cancer cells through the interaction with GKN1, indicating GKN2 as a tumor suppressor." (PMID 34970791, 2022). "We computationally predicted and experimentally validated specific mechanisms of anticancer effects of GKN2 in gastric cancer proliferation and invasion in vitro." (PMID 31463974, 2020). "Generally, GKN2 is downregulated in gastric cancers and has anti-inflammatory and tumor suppressor roles." (PMID 31963721, 2020). "Heterodimeric interaction between TFF1 and GKN2 has been reported to entail synergistic anti-proliferative and pro-apoptotic effects on gastric cancer cells." (PMID 31963721, 2020). "GKN2 also inhibited xenograft tumor growth and was an independent and significant prognostic factor for patients with gastric cancer treated with oxaliplatin." (PMID 31382983, 2019). "The present study aimed to investigate the expression, function and mechanism of action of GKN2 in gastric cancer." (PMID 31382983, 2019). "To investigate if the oxidative stress-induced anti-proliferative and pro-apoptotic effects of GKN2 in gastric cancer cell were TFF1-dependent, we overexpressed or knocked down TFF1 in GKN2-overexpressing and control cells." (PMID 31382983, 2019). "The aim of this study was to investigate the expression of GKN1 and GKN2 genes as probable biomarkers for gastric cancer." (PMID 30774821, 2018). "Over-expression of GKN2 contributed to cell proliferation, migration, and invasion of gastric cancer and arrested the cell cycle at the G1–S transition phase." (PMID 25928635, 2015). "Specifically, gastrokine-2 expression was reduced in 19 (73.07%), 32 (82.05%) and 7 (63.64%) of the 26 diffuse-, 39 intestinal- and 11 mixed-type gastric cancer samples, respectively." (PMID 25270871, 2014). "Previous studies have demonstrated that expression of gastrokine-2 inhibits the proliferation of gastric cancer cells and the progression of gastric cancer in vivo, in a trefoil factor 1-dependent manner." (PMID 25270871, 2014). "The results demonstrated that pcDNA3.1-GDDR restored gastrokine-2 expression levels in gastric cancer cells." (PMID 25270871, 2014).
gastric cancer (continued). "Gastrokine-2 expression was then analyzed in the two gastric cancer cell lines, and it was demonstrated its expression was absent in the SGC-7901 and AGS cells." (PMID 25270871, 2014). "In conclusion, to the best of our knowledge, the data from the current study demonstrated for first time that restoration of gastrokine-2 expression in SGC-7901 gastric cancer cells inhibits cell viability and induces apoptosis." (PMID 25270871, 2014). "In the present study, expression patterns of gastrokine-2 protein were examined in gastric cancer tissues and cell lines." (PMID 25270871, 2014). "Expression of gastrokine-2 was restored in gastric cancer cells in order to assess its effect on cell viability, apoptosis and gene expression." (PMID 25270871, 2014). "Gastrokine-2 expression was analyzed in 76 primary gastric cancer and corresponding normal tissues using western blot analysis." (PMID 25270871, 2014). "We next measured GKN1 or GKN2 mRNA levels in various gastric carcinoma cells lines and in primary normal gastric tissue by qRT-PCR." (PMID 24460791, 2014). "We also show that latent EBV infection further reduces GKN1 and GKN2 expression in AGS gastric carcinoma cells, and that siRNA depletion of EBNA1 partially alleviates this repression." (PMID 24460791, 2014). "Although at much lower levels than primary stomach tissue, GKN1 and GKN2 were both expressed at measurable levels in AGS gastric carcinoma cell lines, with GKN2 expressed at higher levels than all other GC cell lines, or EBV positive B-cell or NPC cell lines." (PMID 24460791, 2014). "Notably, GKN2 increases sensitivity/cell death in response to reactive oxygen species in gastric cancer cell lines." (PMID 39684873, 2024). "For example, ROS and oxidative DNA damage may have anticancer effects in gastric cancer cells because the antioxidant enzyme peroxiredoxin 2 (PRDX2) is suppressed or gastrokine 2 (GKN2) is overexpressed." (PMID 38086844, 2023). "However, the literature reports on GKN2 and cancer‐related research mainly focused on gastric cancer." (PMID 34970791, 2022). "We validated GKN2, an emerging driver of gastric mucosa, through in silico and in vitro perturbation experiments as well as pathological examination of a large number of human gastric cancer specimens." (PMID 31463974, 2020). "The GKN2 is a secretory protein, whose levels decrease in gastric cancer." (PMID 31382983, 2019). "Following further investigation, gastrokine-2 may prove to be a potential target for novel molecular therapies for gastric cancer." (PMID 25270871, 2014). "Expression of gastrokine-2 protein reduced gastric cancer cell viability and induced apoptosis." (PMID 25270871, 2014). "Previous studies have not implicated gastrokine-2 as a putative gastric cancer-specific tumor suppressor gene." (PMID 25270871, 2014). "Reduction or knockout of gastrokine-2 protein expression may contribute to gastric cancer development or progression, as the current study demonstrated that restoration of gastrokine-2 expression induces apoptosis of gastric cancer cells through the extrinsic apoptosis pathway." (PMID 25270871, 2014). "In gastric cancer, HSPA8 interacts with GKN2 to promote oxidative stress-induced apoptosis, inhibit the NF-κB signaling pathway, and activate the JNK signaling pathway." (PMID 34168974, 2021). "Next, we transfected human gastric cancer cell line AGS, with lenti‐virus containing GKN2 (GKN2‐LV), and performed RNA‐sequencing of GKN2‐LV cells with the control (ctrl‐LV)." (PMID 31463974, 2020). "To study the potential role of EBV and EBNA1 in the transcriptional control of GKN1 and GKN2, we generated an EBV positive AGS gastric carcinoma cell line." (PMID 24460791, 2014). "In addition, in the development of gastric cancer in humans and mice, the highly coordinated deletion of GKN1/GKN2 genes and the abnormal expression (deletion) of GKN are closely related to the occurrence of precancerous inflammation and gastric cancer." (PMID 38250608, 2024).
gastric cancer (continued). "For example, expression of gastrokine-2 (GKN2) was significantly down-regulated or absent in gastric cancer cell lines, gastric intestinal metaplasia, and tumor tissues." (PMID 25928635, 2015). "Expression of gastrokine-2 protein was reduced or absent in gastric cancer tissues and gastric cancer cell lines." (PMID 25270871, 2014).
gastric tumor (5 papers, 2009 to 2024). "Due to the important roles of GKN1 and GKN2 genes and their relationship, in the gastric mucosal defense mechanism and their gastric tumor suppressor activity, GKN1 and GKN2 might be reliable biomarkers for detecting GC in early stages." (PMID 30774821, 2018).
dementia (1 paper, 2009). Loss of intellectual abilities interfering with an individual's social and occupational functions. "There are 8 known families; the cancer associated GKN1, GKN2 and LECT1, the three dementia associated ITM2 families, the respiratory disease associated proSP-C, and TNMD." (PMID 19747390, 2009).
Insulin resistance (1 paper, 2022). Increased resistance towards insulin, that is, diminished effectiveness of insulin in reducing blood glucose levels. "Regardless of insulin resistance, the two groups of women with morbid obesity showed upregulation of LYPD8 and downregulation of a greater number of genes, such as REG1B, GKN2, LPL, PNLIPRP2, FKBP5, and CD86, that are related to responses to bacterial stimuli and antimicrobial activity." (PMID 35625760, 2022).
latent infection (1 paper, 2014). "We then showed that Aza-treatment led to the increase expression of GKN1 and GKN2, and that EBV latent infection inhibits Aza activation of GKN2." (PMID 24460791, 2014). "We next asked whether GKN1 or GKN2 mRNA levels were affected by EBV latent infection in AGS cells by comparing RT-qPCR expression levels in AGS relative to AGS-EBV cells." (PMID 24460791, 2014). "To test the effect of EBV latent infection on GKN1 and GKN2 expression, we generated an AGS cell line containing EBV B95.8 bacmid." (PMID 24460791, 2014).
lung carcinoma (1 paper, 2022). "Gastrokine 2 (GKN2) is significantly downregulated in non‐small cell lung cancer (NSCLC) tissues than in normal tissues (NT), as assessed by mRNA microassay; however, the mechanism and clinical value of GKN2 is unknown in NSCLC." (PMID 34970791, 2022). "Currently, no studies have reported GKN2 expression and lung cancer in China or abroad." (PMID 34970791, 2022).
tumor (15 papers, 2009 to 2025). "GKN2-knockout mice exhibit thinner mucus and altered SCFA profiles that reduce muscle glutamate levels and loss of GKN2 drives premalignant gastric inflammation and tumor progression." (PMID 41234396, 2025). "In this study, we addressed the molecular mechanism underlying the tumor suppressor function of GKN2 in GC." (PMID 31382983, 2019). "The altered immune cell composition, particularly the reduction in immunosuppressive MDSCs, may paradoxically create a more inflammatory but less tumor-permissive environment, which could explain why GKN2 loss alone was insufficient for tumor development." (PMID 40673273, 2025). "The cooperative effects between GKN2 loss and STAT3 hyperactivation demonstrate the multihit nature of gastric carcinogenesis and highlight the importance of both tumor suppressor inactivation and oncogenic pathway activation in human disease." (PMID 40673273, 2025). "Others have demonstrated that GKN2 has low expression in tumor tissues and inhibits PDAC progression." (PMID 39684873, 2024). "The GKN2 mRNA and protein expression level in NSCLC was significantly lower than that in the NT, and the GKN2 expression level in large tumors NSCLC was significantly lower than that in the small tumor group." (PMID 34970791, 2022). "We also found GKN2 expressed in lamina propria of gastric mucosa and tumor of the rat suffered from tumors." (PMID 34093815, 2021). "The areas that showed strong expression of GKN2 and Ghrelin, are all located around the blood vessels in the tumor." (PMID 34093815, 2021). "GKN2 mRNA expression was significantly correlated with tumor size and location with p = 0.023 and 0.006, respectively." (PMID 31463974, 2020). "Within node positive patients, tumor weights in the group with median‐low GKN1 or GKN2 expressions were significantly higher than those in the group with median‐high GKN1 expression, but are independent of pathological T stage." (PMID 31463974, 2020). "Loss of GKN2 results in resistance of cells to oxidative stress, which can justify the tumor suppressor function of GKN2." (PMID 31382983, 2019). "While GKN2 is abundantly expressed in surface mucus cells of the normal human stomach, its levels decrease in gastric adenocarcinoma as well as in tumor cell lines." (PMID 31382983, 2019). "The mean tumor weight and volume were significantly lower in the GKN2-overexpressing group than in the control group (overexpressing the empty vector)." (PMID 31382983, 2019). "GKN2, a stomach-specific gene, has been researched upon for more than 10 years; recently, it has been proposed it acts as a tumor suppressor in many human cancer cell lines." (PMID 31382983, 2019). "A cell viability MTT assay was performed, and the results indicated that restoration of gastrokine-2 expression significantly reduced tumor cell viability in the monolayer culture." (PMID 25270871, 2014). "Our mRNA expression data showing high-level mRNA expression only in primary normal gastric tissue are consistent with a role of GKN1 and GKN2 as a tumor suppressor." (PMID 24460791, 2014). "This suggests that GKN1 and GKN2 function at earlier stages in tumor cell evolution, or in more complex tumor microenvironments." (PMID 24460791, 2014). "GKN2 is a gastric-specific secreted protein that is frequently downregulated in human gastric cancer and may function as a tumor suppressor through regulation of epithelial differentiation and inflammatory responses." (PMID 40673273, 2025). "Interestingly, compared to the HE stains, the places that had strong expression of GKN2 and Ghrelin, were located around the blood vessels in the tumor." (PMID 34093815, 2021). "Additionally, we found that the GPL+CUMS rats with tumors not only had strong expression of GKN2 on the luminal side and the lamina propria of the gastric mucosa and tumor, but also had expression of Ghrelin on the luminal side of the gastric mucosa." (PMID 34093815, 2021).
tumor (continued). "In some studies, Ghrelin and GKN2 might have anti-inflammatory effect 53, which were tumor suppressor genes." (PMID 34093815, 2021). "Recent evidence illustrated that GKN1 and GKN2 may play an important role in the preservation of gastric mucosal homeostasis and function as a gastric individual tumor suppressor." (PMID 30774821, 2018). "GKN1 and GKN2 are reported to function as cell growth inhibitors and tumor suppressors in GC." (PMID 24460791, 2014). "Trefoil factor 1 might contribute to the tumor suppressing effects of GKN2." (PMID 31382983, 2019). "In this study, we found that the expression level of GKN2 in NSCLC was significantly lower than its adjacent cancer tissues, and the expression in large tumor (>2 cm) NSCLC was significantly lower than that in small tumors (≤2 cm)." (PMID 34970791, 2022). "The second ranked module, M434, represents downregulation of tumor suppressors such as TFF2, GKN1 and GKN2 in gastric mucosal barrier (GMB) homeostasis in GC." (PMID 31463974, 2020). "GKN2 is a secretory protein of gastric epithelial cells and its expression is remarkably down regulated or absent in GC tumor tissues." (PMID 30774821, 2018). "We speculate that EBNA1 may have a more pronounced effect on GKN1 and GKN2 expression in situations where EBV may infect primary gastric cells where basal expression of GKN1 and GKN2 are high and important for tumor suppression." (PMID 24460791, 2014).
cancer (9 papers, 2009 to 2022). A tumor composed of atypical neoplastic, often pleomorphic cells that invade other tissues. "The authors computationally predicted and experimentally validated specific mechanisms of anti‐cancer effects of GKN2 in GC proliferation and invasion in vitro." (PMID 31463974, 2020). "Exposure to H2O2 for 6 h led to an increase of ROS levels in the cells and pre-treatment with glutathione (GSH) reversed this effect, suggesting that GKN2 plays a role in stress-induced apoptosis in cancer cells." (PMID 31382983, 2019). "It was demonstrated that gastrokine-2 protein expression was reduced in 58 (84.0%) of the 76 cancer tissue samples compared with the corresponding gastric mucosal tissue samples." (PMID 25270871, 2014). "Similarly, the GKN2 protein level was significantly lower in NSCLC than in the adjacent cancer tissues." (PMID 34970791, 2022). "GKN2 overexpression could be used to determine the subgroup of patients to obtain the more favorable outcome of oxaliplatin treatment and might be used as biomarker of the prognosis of this cancer." (PMID 31382983, 2019). "The expression of GKN2 may suppress cancer cell proliferation through a TFF1-dependent manner." (PMID 31382983, 2019). "GKN2 overexpression could be used to determine the subgroup of patients to obtain the more favorable outcome of oxaliplatin treatment and may be used as biomarker of the prognosis of this cancer." (PMID 31382983, 2019). "GKN2 promoter methylation levels in males and females from LUAD patients were higher than the adjacent cancer tissues (p < 0.001, p < 0.001)." (PMID 34970791, 2022). "Further analysis showed that GKN2 promoter methylation level of stage I, II, and III was significantly higher than the adjacent cancer tissues, indicating GKN2 promoter hypermethylation in NSCLC." (PMID 34970791, 2022). "In this study, 27 cancer specimens’ samples were selected to evaluate the altered expression of GKN1 and GKN2 genes." (PMID 30774821, 2018). "GKN2, a small (~ 18 kDa) protein belonging to the BRICHOS protein superfamily, is characterized by an approximately 100 amino acid BRICHOS domain, and plays a role in inflammatory diseases, dementia, and cancer." (PMID 31382983, 2019).
infection (1 paper, 2017). The state of being infected such as from the introduction of a foreign agent such as serum, vaccine, antigenic substance or organism. "In contrast, the expression of Gkn1 and Gkn2 was hardly detectable in non-infected mice and rather increased little for Gkn2 after infection, particularly in Tff1KO mice (data not shown)." (PMID 28604600, 2017).
GKN2 also shares sentences with these, for which no sentence is quoted: asthma (1 paper); cyst (1); gastric adenocarcinoma (1); inflammation (1); lymph node metastasis (1); metastatic carcinoma (1); morbid obesity (1); respiratory disease (1).